TLR4 (toll like receptor 4)
Diseases named in the same sentence as TLR4 in open-access papers (continued):
Sharing a sentence is not in itself a finding about the gene and the disease.
tumor (continued). "DDPP profiling identified that the higher the level of TLR-4 fold change in tumor versus normal tissues, the shorter the survival under treatment with anti-PD-1." (PMID 33911192, 2021). "The gut microbiome primes tumor-infiltrating myeloid cells in a TLR4-dependent manner for enhancing production of ROS upon oxaliplatin treatment, leading to tumor regression." (PMID 34885015, 2021). "The same study also showed that platelets from TLR4-deficient mice secreted less TGF-β and were less efficient in promoting tumor invasion." (PMID 34360659, 2021). "Based on these facts, we decided to study the expression of TLR4 gene across cancers and its relationship with the prognosis of different cancer patients and tumor-infiltrating lymphocytes." (PMID 34631699, 2021). "The immunotherapy results showed that low-dose paclitaxel can inhibit the M2 macrophage phenotype and can induce the M1 phenotype via TLR4 signaling, and clinical doses can kill tumor cells." (PMID 34506251, 2021). "miR-21 is a negative regulator for TLR4 to activate NF-κB and decrease IL-10 production by targeting a pro-inflammatory tumor suppressor PDCD4." (PMID 33618723, 2021). "Chemoresistant GBM cells promote the suppression of TLR4 expression in tumor-infiltrating macrophages that release cytokines such as IL-6 and IL-10 and support a tumor-promoting ME." (PMID 34646780, 2021). "It was first shown that TLR2/TLR4- MyD88-mediated signaling was required for the optimal function of MDSCs and suppression of anti-tumor immunity in models of colon cancer and fibrosarcoma, suggesting an involvement of canonical NF-κB activation." (PMID 33572260, 2021). "On either tumor cells or immune cells, TLR4 is involved in the process of initiation and treatment of cancer." (PMID 34141706, 2021). "FFA stimulates the TLR4/NF-κB signaling pathway in adipose and macrophages and is involved in inflammation and tumor progression." (PMID 33767586, 2021). "As for TLR4, the expression is also reduced in tumor tissue compared to normal tissue (P = 0.077) and surrounding tumor tissue (P = 0.0085)." (PMID 34141706, 2021). "The literature reports that TYROBP, TLR4, and ITGAM are involved in the BP to activate macrophages that have been reported as tumor-associated and as the main component of the immune environment in OS35–37." (PMID 34588497, 2021). "In ALT-100 mAb-treated mice, the levels of phosphor-NFκB in the DU145 and PC3 xenografts were markedly decreased in vivo confirming the involvement of the eNAMPT/TLR4/NFκB signaling pathway in these in vivo PCa xenograft tumor models." (PMID 34959723, 2021). "TLR4 is expressed not only on tumor cells but also on stromal cells and immune cells that play vital role in antitumor in the TME." (PMID 32797726, 2020). "The induction of NETosis involves mechanisms that are activated by HMGB1/TLR4 interactions and tumor-derived IL-8, respectively; NETs enhance tumor invasion via the presentation of proteolytic enzymes, such as MMP-9 and elastase." (PMID 32664328, 2020). "Taken together, the data are consistent with a model in which tumor-dependent remodeling of the fibronectin in the ECM promotes inflammation through the activation of TLR4/NF-κB signaling in NSCLC." (PMID 32231714, 2020). "TLR4, which is expressed in cancer cells and leukocytes, mediates inflammation, which often leads to the suppression of immune functions, inducing tumor immune escape." (PMID 33306717, 2020). "OSCC can also express a range of different TLRs, with high levels of TLR-2 and TLR-4 correlating with tumor progression and chemoresistance, respectively." (PMID 35047983, 2020). "Studies have shown that inhibition of TLR4 signaling in TAMs successfully decreased cytokine production and weakened their tumor-promoting activities." (PMID 32283687, 2020). "Of note was the fetuin‐A‐mediated downregulation of the surface expression of TLR4 in the adhered and spread tumor cells." (PMID 33073533, 2020).
tumor (continued). "The binding of extracellular HMGB1 to TLR4 induces efficient cross-presentation of tumor antigens by DCs." (PMID 32178288, 2020). "Our bioinformatics study and published reports demonstrated that the TLR4/MyD88 signalling pathway plays a vital role in tumour suppression (Kang, Su, Sun, & Zhang, 2018; Murad, 2014)." (PMID 32144747, 2020). "One function of TLR4 is to preserve engulfed tumour antigens from enhanced degradation, and thereby favour antigen presentation." (PMID 32715647, 2020). "Together these findings suggest that strategies to improve sequestration in the tumour with limited leakage are needed, or perhaps the evaluation of TLR4 agonists with less potent activity." (PMID 33352882, 2020). "In vitro and in vivo tumor models showed that paclitaxel reprogrammed M2-TAMs to the M1-like phenotype in a Toll-like-receptor 4 (TLR4)-dependent manner." (PMID 32509781, 2020). "Others have shown that TLR4 signalling in the TME can promote the recruitment of macrophages from the systemic circulation into the tumour environment." (PMID 33352882, 2020). "Various lines of evidence have revealed that TLR4 engagement within a tumor microenvironment can promote either antitumor immunity or tumor progression." (PMID 32023919, 2020). "The study demonstrates that TLR4 mediates the rapid uptake of fetuin‐A by tumor cells to promote rapid adhesion, spreading, growth, motility, and invasion in serum‐free medium." (PMID 33073533, 2020). "Alternatively, plasma membranes of tumor cells have been extracted and coated onto polymeric nanoparticle cores along with the TLR4 agonist MPLA as a tumor cell-mimicking cancer vaccine." (PMID 33679703, 2020). "F. nucleatum infection enhanced the tumor growth of CRC in a TLR4-dependent manner, and the effect involved activation of the IL-6/p-STAT3/c-MYC signaling pathway." (PMID 33488528, 2020). "The experiments were performed using multiple tumor cell lines to underscore the significance of fetuin‐A and TLR4 in the in vitro growth of these cells." (PMID 33073533, 2020). "TLR4 expression was decreased in tumor-derived cells incubated with KMP01D alone and in combination with vitamin D3 (KMP01D and combination of KMP01D and vitamin D3 vs. untreated cells: UICC I–III: p < 0.001)." (PMID 32425932, 2020). "More recently, the combination of senescence-inducing chemotherapy (oxaliplatin or cisplatin) with a TLR4 agonist, the lipid A OM-174, has demonstrated strong anti-tumor efficacy in a model of advanced colon carcinoma." (PMID 32370259, 2020). "We also knocked down TLR4 in tumor cells that express the receptor and assessed the abilities of parental nonsilencing controls as well as knockdown subclones to take up labeled fetuin‐A." (PMID 33073533, 2020). "The licensing of DCs to process and present tumor antigens requires interaction of DAMPs (e.g., HMGB1, HSP70) released from dying tumor cells, with Toll-like receptor 4 (TLR4) on DCs." (PMID 32575843, 2020). "To extend our findings in mice to human HCC, we analyzed TLR4 and AR expression using tissue microarray, containing matched pairs of tumor and peritumoral liver tissue from 22 male and 8 female patients with primary HCC." (PMID 31956356, 2020). "Low-dose paclitaxel changed macrophage phenotype from M2 to M1 through the toll-like receptor (TLR)-4, resulting in tumor growth inhibition." (PMID 33081727, 2020). "Since A20 is derived from murine B cells which are known to express TLR4, we investigated the importance of TLR4 expression on tumor cells by generating a biallelic TLR4 knockout A20 cell line." (PMID 32974162, 2020).
tumor (continued). "Mechanistically, the HFD stimulated the activation of adipose tissue macrophages (ATMs) toward an M1-like phenotype and enhanced ATM tumor phagocytosis in a TLR4-dependent manner." (PMID 33060562, 2020). "They demonstrated that, following TLR4-dependent stimulation with LPS, lysates from both Dox and SK-treated tumor cells enhanced the maturation status of BM-derived DCs, concomitant with the priming of Th1/Th17 effector cells." (PMID 32178288, 2020). "More importantly, we demonstrate that knockdown of TLR4 as well as CLI‐095 was able to effectively inhibit the uptake of labeled fetuin‐A by tumor cells." (PMID 33073533, 2020). "We demonstrated that HFD consumption increased the frequency of M1-like macrophages and inhibited the accumulation of M2-like macrophages in a TLR4-dependent manner in tumor-seeded eFats; however, the total number of macrophages in the eFats was not altered." (PMID 33060562, 2020). "The authors described scattered TLR4-expressing macrophages in the area of the tumor-brain interface." (PMID 31959173, 2020). "TLR4 expression was significantly stronger in the normal mucosa and in lymph node metastases compared with that in the tumor." (PMID 32424768, 2020). "In this study, we first found that THBS2/TLR4 interaction promotes the tumor growth of CRC by enhanced HIF-1α-mediated glycolysis." (PMID 33244454, 2020). "In epithelial OC, TLR-4 signaling has been demonstrated to promote tumor growth and to develop chemoresistance." (PMID 32455705, 2020). "These DAMPs work primarily through a TLR4/NF-κB pathway to promote chronic inflammation and to drive the expression of growth and survival genes all of which are thought to contribute to tumor progression." (PMID 31952223, 2020). "Taken together, the data show that TLR4 expressed by a variety of tumor cells plays a role in the rapid uptake of fetuin‐A by these cells." (PMID 33073533, 2020). "Inhibition of TLR4 by CLI‐095 also attenuated the rapid adhesion of tumor cells as well as invasion through a bed of Matrigel." (PMID 33073533, 2020). "Promotion of the TLR-4/NF-κB axis in APC causes intensive secretion of chemokines and proinflammatory molecules to the tumor microenvironment." (PMID 32354122, 2020). "OVA/TLR4 mAb can enhance the anti-tumor effect of anti-PD-1 mAb by activating OVA-specific CD8+ T-cells." (PMID 33469538, 2020). "Despite their protumor activity, TLR2 and TLR4 have been studied as components of adjuvants for vaccination and tumor therapy." (PMID 32012718, 2020). "So, the production of factors induced by TLR4 signaling is a way to tumor evasion from immune surveillance." (PMID 33469538, 2020). "Recent studies have reported that the extracellular matrix (ECM)-driven DAMPs contributed to the activation of TLR4 signaling during the tumor progression." (PMID 32850794, 2020). "Typically, tumor cells commonly express TLR4 and the activation of TLR4 signaling leads to the cytoskeletal alteration and subsequent, the generation of T‐MPs through cellular membrane shedding." (PMID 32976623, 2020). "Volcano plots were created to visualize the significant differential up‐regulation and down‐regulation genes in the gut tumours of ApcMin/+ TLR4−/− mice compared with ApcMin/+ WT mice." (PMID 31650683, 2020). "We focus on the killing effect and mechanisms of macrophages on tumors, while tumor promoting factors such as IL-6, IL-8, IL-10, TLR4 are briefly introduced as well." (PMID 32161718, 2020). "During the early stage of oral tongue squamous cell carcinoma, TLR2 and TLR4 expressions serve as predictive markers of invasive tumor growth and a higher tumor grade." (PMID 32424768, 2020). "Further, high-mobility group box 1 (HMGB1), released by dying tumor cells, interacts with TLR4 on platelets and mediates platelet–tumor cell interaction, which promotes metastasis." (PMID 32244723, 2020).
tumor (continued). "The tumor-derived intermediate-sized hyaluronan fragments have been recently reported to induce M2 macrophage polarization via the TLR4/mir-935 pathway to promote tumor progression." (PMID 32788720, 2020). "We further show that the release of IL-8 by NSCLC cells seeded onto tumor-associated ECM is dependent on fibronectin, NF-κB and TLR4." (PMID 32231714, 2020). "We show here that the TLR4 positive human B-lymphoma cell line Mino responds to TLR4 stimulation in a very similar fashion to the murine A20 tumor cell line." (PMID 32974162, 2020). "The proposed activation of TLR4 and subsequent release of IL-8 in response to strained fibronectin present in the tumor stroma is significant." (PMID 31952223, 2020). "After a series of validation experiments for the concerned genes, it was found that IL6, GM‐CSF (CSF2), IL11, CCL3, S100A8 and S100A9 were significantly decreased in the gut tumours of ApcMin/+ TLR4−/− mice compared with ApcMin/+ WT mice." (PMID 31650683, 2020). "The in vivo experiment showed that Selene exhibited minimal effects on suppressing ascites and inducing tumor cell apoptosis when TLR4 and TRAF3 were knocked down." (PMID 32802180, 2020). "The inhibitory effect of the HFD on tumor seeding was abolished with the ablation of macrophages, inactivation of T cells, or blockade of the TLR4–Cxcl10 axis in macrophages." (PMID 33060562, 2020). "Recently, it was described that TLR4 is required for the induction of antitumor immune responses, and tumor regression in patients with carcinoma." (PMID 32448225, 2020). "Strikingly, both the direct effect of GLA on tumor cells (upregulation of activation markers, induction of apoptosis) and the clinical effect of intratumoral G100 injection (tumor shrinkage) were completely abrogated in the TLR4 k.o. model." (PMID 32974162, 2020). "A side-by-side comparison of IT G100 effect on WT A20 tumor vs. TLR4 k.o. tumors showed that the in vivo anti-tumor effects of G100 were entirely dependent on expression of TLR4." (PMID 32974162, 2020). "The in vivo experiment indicated that blocking THBS2/TLR4 interaction significantly extends the survival of tumor-bearing mice." (PMID 33244454, 2020). "Consistently, the HFD-stimulated infiltration of total, CD4+, and CD8+ T cells into tumor-seeded eFats was prevented in TLR4-cko mice." (PMID 33060562, 2020). "The answer would help us understand the interaction between ERβ and TLR4 in tumor progression more clearly and provide evidence for a new therapeutic strategy for clinical patients suffering from advanced metastatic NSCLC." (PMID 32367494, 2020). "In a previous study, it was shown that TLR4 plays an important role in the molecular mechanism of Salmonella choleraesuis (S. choleraesuis)-induced host anti-tumor responses." (PMID 32194422, 2020). "To investigate the possibility that G100-stimulated B-tumor cells would participate in the induction of antitumor responses, we first determined that the cells had an intermediate level of TLR4 expression at baseline as measured by flow cytometry." (PMID 32974162, 2020). "While several other studies provided evidence that TLRs ligands such as lipopolysaccharide (LPS) was associated with epithelial-to-mesenchymal transition (EMT) and accelerated metastatic tumor growth through TLR4." (PMID 33363472, 2020). "We hereby provide experimental evidence that TLR4 participates in the rapid uptake of fetuin‐A by tumor cells resulting in rapid attachment and spreading of cells on substrata." (PMID 33073533, 2020). "HMGB1 is utilized by tumor cells to divert the potentially protective activities of the innate immune system, specifically those involving activation of TLR4, as well as RAGE, to generate a hyperinflammatory, immunosuppressive, protumorigenic TME." (PMID 32664328, 2020). "Pancreatic microenvironment is abundant in TLR4 ligands, including HMGB1 and S100A9, that can activate TLR4 signaling in tumor cells." (PMID 32516941, 2020).
tumor (continued). "Our study shows that the expression of TLR4 was reduced in PBMCs and tumor-derived cells from CRC patients following ex vivo incubation with KMP01D." (PMID 32425932, 2020). "MGLL can inhibit CB2 cannabinoid receptor-dependent tumor progression, and CB2 antagonist treatment can delay tumor progression in mice, which indicates that TLR4 activation can also inhibit tumor growth." (PMID 33224886, 2020). "Ceramide was identified as a TLR4 agonist and has been demonstrated to be a powerful tumor suppressor." (PMID 31775862, 2019). "In other words, TLR4 expression in DCs is essential for the induction of a sustained immune response against dying tumor cells and for the success of radiotherapy and chemotherapy approaches." (PMID 30699928, 2019). "Several studies have highlighted that activation of toll-like receptor 4 (TLR4) in tumors and stromal cells effects tumor progression and evasion from immune surveillance." (PMID 31739536, 2019). "LPS binds to TLR4 in tumor tissues and induces the synthesis of a variety of inflammatory mediators, including TNFa, IL8 and multiple chemokines." (PMID 30636642, 2019). "β-Lapachone-induced high mobility group box 1 (HMGB1) release activates the host TLR4/MyD88/type I interferon pathway and Batf3 dendritic cell-dependent cross-priming to bridge innate and adaptive immune responses against the tumor." (PMID 31324798, 2019). "This concept has indicated that TLR4-priming results in polarization of MSCs into a pro-inflammatory phenotype or MSC 1 which has shown to exhibit anti-tumor properties." (PMID 31857958, 2019). "Instead, exosomes produced by tumor cells after TLR4 activation were always immunosuppressive, suggesting that the treatment influences TEX cargo." (PMID 31186484, 2019). "These included inflammatory mediators related to protection against bacterial infection (Il1α, Tlr4, Lyz2, Mpo), all of which increased in brains of tumor-bearing mice relative to tumor-free controls during the dark phase only." (PMID 31019214, 2019). "Tumors tended to increase Tlr4 gene expression relative to controls and tumor-resected mice (p = 0.06) during the dark phase only." (PMID 31019214, 2019). "Our results suggest that the activation of TLR4 supports tumor progression by stimulating the release of more effective immunosuppressive exosomes, which allow tumor cells to escape immune surveillance and probably even play a role in the metastatic process." (PMID 31186484, 2019). "Of these cells, the role of hepatic stellate cells (HSC) has been extensively investigated in the development of liver inflammation, fibrosis and subsequent tumor via TLR4." (PMID 31068809, 2019). "We observed that MIP induced significant tumor regression in TLR4−/− mice, but its antitumor efficacy was substantially reduced in TLR2−/− mice." (PMID 31590685, 2019). "MC38 tumor cells were s.c. implanted into WT or Tlr4−/− or Myd88−/− C57BL/6 mice, and tumor-bearing mice were treated with β-lap with or without anti-HMGB1Ab." (PMID 31324798, 2019). "Experiments with TLR knockout mice demonstrated that MIP induced comparable tumor regression in wild-type and TLR4−/− mice." (PMID 31590685, 2019). "In our previous studies, not only RPS3, but also several ribosomal proteins that bind to TLR4 were screened from human tumor cells." (PMID 30819254, 2019). "As an important protein in the innate immune response, TLR4 is expressed in many important tumor cells and immune cells, which is also involved in the antitumor functions of some traditional Chinese medicine." (PMID 30992392, 2019). "We assumed that TLR4 signaling usurped through intestinal DC of U14-bearing mice, triggered tumor self-protection mechanisms and then led to immune escape." (PMID 31277622, 2019). "HSPA8 has been reported have to anti-tumor effects by inducing chemokine production from tumor cells and activation of chemo-attracted dendritic cells via the TLR4 pathway in mice." (PMID 30918657, 2019).